CXCR4 (C-X-C motif chemokine receptor 4)
Diseases named in the same sentence as CXCR4 in open-access papers (continued):
Sharing a sentence is not in itself a finding about the gene and the disease.
leukemia (continued). "By expressing two CXCR4 mutated variants in AML cells with disrupted endogenous Cxcr4, we could show that CXCR4 signaling, but not CXCL12 binding, is essential for MLL-AF9 leukemia cells in vivo." (PMID 32460032, 2020). "Interestingly, expression of the signaling-dead variant of CXCR4, CXCR4L251P, failed to rescue depletion of leukemia cells in the bone marrow and spleen, demonstrating that CXCR4 signaling is essential for leukemia cells." (PMID 32460032, 2020). "As a consequence of these actions decreasing CXCR4 expression, migration capacity of NK cells toward the CXCR4 ligand SDF-1α decreased in vitro, which would be expected to reduce the potential of these cells to infiltrate BM compartments where malignancies such leukemia and myeloma reside." (PMID 31231387, 2019). "Therefore, CXCR4 antagonism can be hypothesized in T-ALL treatment, also against early circulating leukemia cells." (PMID 31346528, 2019). "Finally, leukemia cells have been demonstrated to be trapped in stem cell niches of the bone marrow, and follicular lymphoma stem(-like) cells to follicular DCs in the germinal center of lymph nodes by SDF-1/CXCR4 signaling." (PMID 30622535, 2018). "Therefore, the use of CXCR4 antagonists may be a means to improve outcome in infant MLL-R ALL by targeting MRD and leukemia-initiating cells (LIC)." (PMID 26360610, 2015). "Interestingly, HCMV proteins UL33 and UL78 have been shown to modulate surface CXCR4 level without altering total CXCR4 expression in leukemia cells in vitro." (PMID 23555768, 2013). "Additionally, small molecule inhibitors targeting the tumor microenvironment, such as C-X-C chemokine receptor type 4 (CXCR4) antagonists or angiotensin II receptor blockers, have been demonstrated to enhance the infiltration and functional activity of CAR-Ts in the context of leukemia." (PMID 39329777, 2024). "Based on this result, the level of CXCR4, the SDF-1 receptor, in leukemia cells was further examined, finding that in the co-culture system, up-regulation of IFI6 could significantly increase the leukemia cell level of CXCR4, while down-regulation of IFI6 yielded the opposite results." (PMID 37670388, 2023). "This is in line with other (clinical) studies showing promising results by inhibiting CXCR4 in AML or even proposing that the blockade of CDK family members, e.g., with palbociclib, could be a beneficial treatment option in combination with NOTCH1 inhibition for leukemia." (PMID 37833915, 2023). "In addition to CXCR4, we then speculated that the changes in the number and position of GFP-NALM-6 cells homed to the BM was due to the disruption of interactions between leukaemia cells and components of bone marrow matrix." (PMID 38798305, 2022). "However, by culturing leukemia cells under low stimulatory conditions without cytokines, mild but significant depletion of Cxcr4 sgRNA-expressing GFP+ leukemia cells was observed, suggesting that CXCR4 provides signaling that supportscellular growth and survival." (PMID 32460032, 2020). "Furthermore, overexpression of all selected miRs lowered uPAR/CXCR4 expression in THP-1 cells and, viceversa, the specific inhibition of all three miRs increased uPAR/CXCR4 expression in KG1 cells, confirming a functional role of selected miRs in leukaemia cell lines." (PMID 26082201, 2015). "Previous studies have demonstrated that several adhesion molecules and chemokines, including CXCR4, CD56, CD44, CCR7, and VLA-4, contribute to the harboring and proliferation of leukemic cells in the BM niche and may enhance niche-mediated resistance in leukemia." (PMID 22069486, 2011). "Further, when control cells (shControl) were preincubated with CXCR4 antagonist (AMD3100), prior to the chemotaxis assay, CXCL12 was no longer able to induce leukemia cells migration." (PMID 33842460, 2021).
leukemia (continued). "Taken together, our data suggest that CXCR4 signaling is essential for growth and survival of MLL-AF9 leukemia cells independent of CXCL12, MIF, and UBIQUITIN stimulation." (PMID 32460032, 2020). "Expression of other cell surface molecules that were shown to regulate hematopoietic and leukemia stem cells, EPCR, CXCR4 and CD49d, were not upregulated by DS-5272." (PMID 31653912, 2019). "We first analyzed the CXCR4 and ACKR3 cell surface expression levels in CHO-K1, HEK293T and THP-1 cells (with no to low CXCR4 expression), and Raji, Jurkat and CCRF-CEM human leukemia/lymphoma-derived cell lines (endogenously expressing high levels of CXCR4) by flow cytometry." (PMID 41402431, 2025). "We report the novel findings that despite an intact CXCR4 signaling pathway, CALM-AF10 carrying leukemia cells do not show additive nor synergistic cytotoxic or anti-proliferative effects upon combinatorial inhibition of CXCR4 and traditional chemotherapeutics." (PMID 35070954, 2021). "ARV-825 resulted in reduced BETP-dependent transcription of chemokine receptors, indicated by downregulation of surface CXCR4 and CD44 in leukemia stem cell populations, thereby reducing CD34+CD38– putative leukemia progenitor cell populations without affecting healthy BM–derived progenitor cells." (PMID 33466790, 2021). "Monomethyl auristatin E conjugated with the CXCR4‐targeted protein nanoparticles could be utilized to kill CXCR4+ AML cells and to reduce leukaemia burden in mice without the severe toxicity of classical AML therapeutic drugs." (PMID 34050566, 2021). "Although CXCR4 has been shown to regulate leukemia-initiating cells in T cell acute lymphoblastic leukemia, the functional role of CXCR4 in AML development has remained elusive and has so far not been investigated using genetic deletion of Cxcr4 in AML cells." (PMID 32460032, 2020). "Although the SDF‐1/CXCR4 pathway is critical for the homing to and retention of leukaemia cells in the BM, drug‐resistant MLL‐AF9 AML cells in BM were not affected by AMD3100, and BCP‐ALL cell chemotaxis towards the leukaemia niche was independent of SDF‐1/CXCR4." (PMID 34050566, 2021).
HIV-1 infection (221 papers, 2005 to 2026). The type species of lentivirus and the etiologic agent of acquired immunodeficiency syndrome (AIDS). "In this study, we found that HSPCs are susceptible to CXCR4-tropic HIV-1 infection during their in vitro differentiation toward mature megakaryocytes." (PMID 39354676, 2025). "More interestingly, HIV-1 infection caused a more significant increase in CXCR4 levels, but its levels were comparable to uninfected controls in hCOs infected with HIV-1 and treated with cART regimen." (PMID 38600307, 2024). "These cells remained susceptible to HIV-1 infection by CXCR4-tropic strains but were resistant to challenge with CCR5-tropic strains, suggesting that their editing was CCR5-specific and did not overtly alter cell viability." (PMID 36015010, 2022). "As macrophages express the HIV-1 entry receptor CD4 and co-receptors CCR5 and CXCR4, they are themselves susceptible to HIV-1 infection." (PMID 33669846, 2021). "A recent study using a humanized mouse model further described depletion of bone marrow CD34+ cells following CCR5-tropic HIV-1 infection in a CXCR4-associated manner." (PMID 30761146, 2019). "ZFN-modified CXCR4-deficient cells, by contrast, demonstrated selective advantage when challenged with HIV-1 infection both in vitro and in vivo." (PMID 30619107, 2018). "In summary, the combination of CRISPR-Cas9 to edit the CXCR4 gene at a functional site and inducing piggyBac transposon-mediated HR events can efficiently generate a CXCR4 P191A mutation in the genome, which confers less efficient HIV-1 infection." (PMID 29872154, 2018). "Many studies have reported that primary HIV-1-infected patients mainly have CCR5-tropic HIV-1 viruses (R5 viruses) while about half of the patients in the late stage of HIV-1 infection have both R5 viruses and CXCR4-tropic HIV-1 variants (X4 variants)." (PMID 28472121, 2017). "CXCR4 is a co-receptor for human immunodeficiency virus type 1 (HIV-1) entry, and loss of CXCR4 function can protect cells from CXCR4 (X4)-tropic HIV-1 infection, making CXCR4 an important target for HIV-1 gene therapy." (PMID 29141633, 2017). "CIB1 and CIB2 knockdown was found to reduce the expression of surface molecules implicated in HIV-1 infection, including CXCR4, CCR5 and integrin α4β7, suggesting at least one mechanism through which these proteins promote viral infection." (PMID 27489023, 2016). "Our results thus suggest that low CD4 and high CXCR4 expression both contribute to the high susceptibility of T cells from the elderly to HIV-1 infection." (PMID 26452480, 2015). "The increased susceptibility of T cells from the elderly to HIV-1 infection correlated directly with CXCR4 and inversely with CD4 expression." (PMID 26452480, 2015). "On the one hand, increased levels of T cell activation and CXCR4 cell surface expression together with reduced CD4 expression levels render CD4+ T cells from the elderly highly susceptible to HIV-1 infection and replication." (PMID 26452480, 2015). "The emergence of detectable CXCR4-using variants during HIV-1 infection is a major determinant for disease progression, but is still poorly understood." (PMID 21731496, 2011). "CXCR4 tropism has been associated with escape from neutralizing antibody response both in HIV-1 infection and HIV-2." (PMID 21969855, 2011). "Further studies with sequential follow up samples from children will clarify if the association with CXCR4 switch occurs also in pediatric HIV-1 infection." (PMID 18820725, 2008). "During HIV-1 infection coreceptor switch from CCR5- (R5)- to CXCR4 (X4)-using viruses is associated with disease progression." (PMID 17895991, 2007). "In 40–50% of infected adults, progression of HIV-1 infection is accompanied by a switch in coreceptor specificity to HIV-1 variants able to use CXCR4 or both CCR5 and CXCR4 for entry (X4 or R5X4 strains, respectively)." (PMID 17634131, 2007).
HIV-1 infection (continued). "CXCR4 may be targeted to protect HSPCs against CXCR4-tropic HIV-1 infection, because they express CXCR4 and are considered susceptible to CXCR4-tropic HIV-1 infection." (PMID 32154191, 2020). "We found that EBV, which transforms B cells, renders them susceptible to HIV-1 infection in a CXCR4 and CD4-dependent manner in vitro and that CXCR4-tropic HIV-1 integrates into the genome of these B cells with the same molecular profile as in autologous CD4+ T cells." (PMID 32576602, 2020). "Other research groups have reported that the loss of CD34+ cells in CCR5-tropic HIV-1 infection might be dependent on plasmacytoid dendritic cells (pDCs) or correlated with CXCR4 expression (Tsukamoto, 2018)." (PMID 32154191, 2020). "In addition, a recent humanized mouse study indicated the involvement of CXCR4 in the loss of BM HSPCs in CCR5-tropic HIV-1 infection (Tsukamoto, 2018)." (PMID 32154191, 2020). "On the other hand, the present study utilizing coculture of HIV-infected CD34+ cells and OP9-DL1 showed that CXCR4-tropic HIV-1 infection may also cause rapid depletion of CD34+CD7+CXCR4+ cells." (PMID 30761146, 2019). "We cannot exclude the possibility that astrocytes in situ exposed to the neural tissue environment may be induced to express CD4 and CCR5 and therefore, along with endogenous CXCR4 expression, be susceptible to HIV-1 infection in vivo." (PMID 28178524, 2017). "Overall, these differences in viral tropism may explain the differential contribution of the TN CD4+ T-cell subset to the total pool of infected cells in each subject, as their susceptibility to HIV-1 infection is highly dependent on CXCR4 co-receptor usage." (PMID 27484989, 2016). "Further, the observations in CXCR4-tropic vif-deficient HIV-1-infected BLT mice may occur only the late stage of HIV-1 infection in patients." (PMID 25807049, 2015). "Although activated CD4+ T cells are generally considered to be prime targets for HIV-1 infection and replication, cellular susceptibility to HIV-1 infection requires the expression of either the CCR5 (in early infection) or CXCR4 (in late infection) co-receptor." (PMID 22214232, 2012). "Although naïve T cells show lower levels of CCR5 expression and higher levels of CXCR4 in comparison to memory cells, they were shown to possess a higher in vitro susceptibility to R5 HIV-1 infection than memory T cells following stimulation with immobilized anti-CD3 plus anti-CD28 Ab." (PMID 21284907, 2011). "In peripheral blood, the high proportion of CCR5+CD4+ T cells that are recruited during acute HIV- 1 infection may favor R5 variants to replicate and thereby outcompete putative co-transmitted CXCR4-using variants." (PMID 21284904, 2011). "Although previous in vitro assays demonstrated susceptibility of HSPCs to HIV-1 infection and suggested pathogenic roles of CXCR4-tropic HIV-1, some of those assays relied on strong in vitro cytokine stimulation of HSPCs that may cause significant upregulation of HIV-1 (co)receptors." (PMID 30761146, 2019). "Our findings establish a link between CXCR4 clustering and HIV-1 infection, enhancing our understanding of the initial events in viral attachment and entry." (PMID 42118136, 2026). "In contrast, JM#21 suppresses CXCR4-tropic HIV-1 infection more efficiently than the clinically approved small-molecule CXCR4 antagonist AMD3100." (PMID 40076664, 2025). "HIV-1 infection with the CXCR4-tropic strain was performed on Day 7 of the 14-day megakaryocyte differentiation regimen, in line with what has been reported previously." (PMID 39354676, 2025). "In HIV-1 infection, CXCR4 predominantly manifests at the advanced stages, correlating with rapid CD4+ T cell depletion and disease progression." (PMID 40075611, 2025). "Worthy of note, in addition to be a marker of granulocyte maturation, CXCR4 is also important for HIV-1 infection, as it is one of the co-receptors for the virus entry." (PMID 38384451, 2024).
HIV-1 infection (continued). "In biomedical studies, CXCR4 serves as the therapeutic target of cancer metastasis and HIV-1 infection." (PMID 38540757, 2024). "Gene-editing of CXCR4 has also been a target for a curative solution for the CXCR4-tropic HIV-1 infections." (PMID 38741006, 2024). "The combined HIV-1 therapeutic genes were investigated for the potential prevention of both CCR5 (R5)- and CXCR4 (X4)-tropic HIV-1 infections in the MT4CCR5 cell line." (PMID 38741006, 2024). "Here, we describe a novel allosteric CXCR4 antagonist TIQ-15 which inhibits CXCR4-tropic HIV-1 infection of primary and transformed CD4 T cells." (PMID 39146384, 2024). "The chemokine receptor CXCR4 has become an attractive therapeutic target for HIV-1 infection, hematopoietic stem cell mobilization, and cancer metastasis." (PMID 38131305, 2023). "The targeted protein CXCR4 (PDB: 3OE0) is a critical regulator of inflammation and immune surveillance implicated explicitly in cancer metastasis and HIV-1 infection." (PMID 37047831, 2023). "Despite their remarkable resistance to CCR5 (R5)-tropic HIV-1 infection, TEMRA cells remain highly susceptible to CXCR4 (X4)-tropic HIV-1 infection." (PMID 37901239, 2023). "This unique inhibitor demonstrates the ability to impede HIV-1 infection and halt CXCR4-dependent processes such as tumor cell migration and invagination." (PMID 38003419, 2023). "M-tropic strains of HIV-1, which use CCR5 as a co-receptor, participate in the early stage of HIV-1 infection whereas T-tropic strains of HIV-1 using another co-receptor CXCR4 are involved in the late stage of viral infection." (PMID 38131305, 2023). "CEM/R5 cells expressing HA-CXCR4 were relatively sensitive to X4- and R5-tropic HIV-1 infection, suggesting that KI-based N-terminal modification preserved the function of CXCR4 at least at the level of viral coreceptors." (PMID 35073736, 2022). "Although the other HIV-1 coreceptor, CXCR4, has also been targeted by Cas9, CXCR4 modified cells showed resistance against HIV-1 infection." (PMID 35572626, 2022). "Previous reports have demonstrated expression of CXCR4 on astrocytes and neurons; however, this observation appears to have little relevance to HIV-1 infection given that these cells lack CD4." (PMID 35975998, 2022). "We observed that overexpression of wt-TDP-43 did not significantly change the cell-surface expression levels of CD4, CCR5 and CXCR4 molecules (i.e., main receptor and co-receptors for HIV-1 infection, respectively)." (PMID 35682862, 2022). "In summary, our data confirm that primitive HSPC subpopulations are susceptible to CXCR4- and CCR5-mediated HIV-1 infection in vitro and in vivo, which qualifies these cells to contribute to the HIV-1 reservoir in patients." (PMID 36230931, 2022). "Some studies have performed CCR5 or CXCR4 ablation in CD4+ TRM cells using CRISPR-Cas9 to protect cells against CCR5 or CXCR4 tropic HIV-1 infection." (PMID 35664434, 2022). "They showed that CXCR4-tropic or CCR5-tropic HIV-1 infections were significantly reduced in CXCR4- and CCR5-modified cells." (PMID 35628210, 2022). "CXCL12 within mucosa and lymph nodes was proposed to counter-select transmission of CXCR4-using viruses, thereby contributing to preponderance of R5 viruses in the first stages of HIV-1 infection." (PMID 33872329, 2021). "In HIV infection, IL-4 differentially regulates the expression of CCR5 and CXCR4 co-receptors, which play a key role in HIV-1 infection, preventing the virus from entering the cell and its replication." (PMID 34835417, 2021). "In primary human CD4+ T cells and in U87-MG.CD4+CXCR4+ cells transduced to ectopically express huTRIM5α, HIV-1 infection was efficiently inhibited in the presence of IFNα, in a manner dependent on SPRY domain-mediated recognition of the viral capsid." (PMID 33669846, 2021). "The CD4 receptor protein and CCR5 and CXCR4 coreceptors are critical for HIV-1 infection and act as barriers to restrict HIV-1 adhesion and entry into target cells." (PMID 34076481, 2021).